SMC1A (structural maintenance of chromosomes 1A)
Diseases named in the same sentence as SMC1A in open-access papers (continued):
Sharing a sentence is not in itself a finding about the gene and the disease.
acute myeloid leukemia (9 papers, 2021 to 2024). Acute myeloid leukemia (AML) is a group of neoplasms arising from precursor cells committed to the myeloid cell-line differentiation. "Here, we investigate a recurrent missense mutation to the hinge domain of the cohesin subunit SMC1A, observed in acute myeloid leukemia." (PMID 33760811, 2021). "Interestingly, SMC1A mutations have adverse prognostic relevance in acute myeloid leukemia (AML) resulting in significantly shorter overall survival." (PMID 35287703, 2022). "However, low SMC1A expression in acute myeloid leukemia is associated with the poor prognosis." (PMID 35372377, 2022). "Using the COSMIC cancer-genome database we identified a recurrent R-to-W mutation at SMC1A amino acid residue 586 that occurred almost exclusively in the context of acute myeloid leukemia (AML)." (PMID 33760811, 2021). "However, it has been reported that patients with acute myeloid leukemia who express of SMC1A poorly have a poor prognosis for survival." (PMID 37537540, 2023). "However, SMC1A is downregulated in acute myeloid leukemia, and its low expression indicates a poor prognosis." (PMID 37537540, 2023). "Mutations in the cohesin complex components (STAG2, RAD21, SMC1A, SMC3, and PDS5B) are recurrent genetic drivers in myelodysplastic neoplasm (MDS) and acute myeloid leukemia (AML)." (PMID 39033241, 2024). "The genetics of cohesinopathy provide evidence for RAD21, STAG2, SMC1A, and SMC3 as driver mutations in acute myeloid leukemia (AML), chronic myeloid leukemia (CML), and pre-leukemic states (myelodysplastic syndrome; MDS)." (PMID 35902807, 2022). "In some forms of acute myeloid leukemia (AML), the cumulative level of mutations in RAD21, SMC1a, SMC3, and STAG2 genes reaches 13%." (PMID 35353576, 2022). "In addition, affinity purification of the cohesin complex with Smc1a antibody in human acute myeloid leukemia (AML) cells, followed by mass spectrometry, identified Matr3." (PMID 34716321, 2021). "For example, somatic mutations in the eight genes that comprise the cohesin ring (SMC1A, SMC3, STAG1, STAG2, RAD21) and the cohesin-ring support genes (NIPBL, MAU2, WAPL, PDS5A, PDS5B) and CTCF are frequently found in many cancer types and are especially common in acute myeloid leukemia (AML)." (PMID 36171609, 2022).
colon carcinoma (8 papers, 2009 to 2024). "Further, we collected 37 cases of colon cancer and paired paraneoplastic tissues and performed RT‐qPCR assays for the expression levels of SMC1A and miR‐23b‐3p in the tissues." (PMID 37096492, 2023). "Similar signals for SMC1A have been detected using signal amplification methods in the human colon cancer cell line HCT-11621." (PMID 38040722, 2023). "This implies that SMC1A presented a positive correlation with the “hot” immune environment in colon cancer." (PMID 37096492, 2023). "Our results showed that the mRNA levels of SMC1A were significantly increased in colon cancer tissues compared with paraneoplastic tissues." (PMID 37096492, 2023). "The effects of SMC1A silencing on the development of colon tumors were analyzed in vivo using nude mouse models." (PMID 25884313, 2015). "We have known that high SMC1A expression was positively correlated with immune cell infiltration, especially T‐cell immune cell infiltration, that is, SMC1A was in the “hot” T‐cell inflammatory microenvironment in colon cancer." (PMID 37096492, 2023). "In addition to SMC1A in the “hot” T‐cell inflammatory microenvironment of colon cancer, SMC1A also positively correlates with the immune checkpoint genes CD274, CTLA4, and PDCD1 in colon adenocarcinoma (COAD) samples." (PMID 37096492, 2023). "In the present study, we found that SMC1A was expressed in a multitude of immune cells, especially in proliferating T cells, and SMC1A expression in colon cancer could affect T‐cell proliferation." (PMID 37096492, 2023). "Similarly, SMC1A protein expression was increased in colon cancer tissues in the mass spectrometry‐based proteomics of the CPTAC database." (PMID 37096492, 2023). "In addition, SMC1A expression in colon cancer was much higher than that in rectal cancer (p < 0.001)." (PMID 25884313, 2015). "Additionally, the potential use of RNAi-mediated SMC1A gene knockdown as a therapeutic target against colon cancer progression was analyzed using in vitro and in vivo colon cancer cell models." (PMID 25884313, 2015). "Previous studies reported that upregulated SMC1A might be associated with glioblastoma, lung cancer and colon cancer progression, but the expression and prognosis of SMC1A in sarcoma had not been investigated to date." (PMID 33460400, 2020). "Among them, only miR‐23b‐3p was significantly downregulated in colon cancer tissues compared with normal tissues, and miR‐23b‐3p and SMC1A showed a significant negative correlation in COAD samples." (PMID 37096492, 2023).
breast carcinoma (6 papers, 2013 to 2025). "Expression and cellular localization of p-SMC1A was also tested in a panel of breast cancer and normal epithelial cells by immunocytochemistry (ICC), flow cytometry and on-cell Western analysis." (PMID 39851557, 2025). "Our results revealed that p-SMC1A staining intensity was lower in normal breast tissues compared to invasive or metastatic breast cancer tissues (p < 0.001)." (PMID 39851557, 2025). "Approximately 40% of breast cancer tissue exhibited cytoplasmic/membranous localization of p-SMC1A, whereas nuclear expression was observed in normal breast tissues." (PMID 39851557, 2025). "Overall, these results showed that SMC1A was aberrantly phosphorylated in breast cancer cells and phosphorylated SMC1A mislocalized to the cytoplasm and membrane of some cancer cells." (PMID 39851557, 2025). "Despite these insights, the precise role of SMC1A phosphorylation in breast cancer remains largely unexplored." (PMID 39851557, 2025). "This study represents the first investigation to test the phosphorylation status and subcellular localization of SMC1A (p-SMC1A) in breast cancer and normal breast tissues." (PMID 39851557, 2025). "Our results showed that SMC1A was aberrantly phosphorylated in breast cancer cells, and the phosphorylated protein mislocalized to the cytoplasm and membrane of selected cancer cells and not the normal cells." (PMID 39851557, 2025). "While low to no phosphorylation of SMC1A was found on the surface of normal epithelial cells, we found aberrant phosphorylation of SMC1A on the surface of breast cancer cells known to have a high rate of proliferation." (PMID 39851557, 2025). "We found a positive correlation of SMC1A phosphorylation with tumor progression, suggesting a potential role of this molecule in the initiation and progression of breast cancer." (PMID 39851557, 2025). "The membranous expression of pSMC1A was further tested on breast cancer and normal epithelial cells by flow cytometry using SMC1A and pSMC1A (Ser966) antibodies as described in the Methods section." (PMID 39851557, 2025). "We also tested the expression of p-SMC1A protein in membranous, cytoplasmic, and nuclear fractions of breast cancer and normal epithelial cells by cellular fractionation and Western blot." (PMID 39851557, 2025). "This is because SMC1A has been shown to bind to the promoter region of the SNAIL gene in breast cancer cells." (PMID 37537540, 2023). "This suggests that SMC1A phosphorylation may play a pivotal role in cancer progression; however, its significance in breast cancer remains uncertain." (PMID 39851557, 2025). "Our current results support the potential role of SMC1A phosphorylation in breast cancer progression, and p-SMC1A may have prognostic value in breast cancer patients." (PMID 39851557, 2025). "We first determined if the SMC1A 1^4 FS peptide confers protection in the B16F10 mouse melanoma cancer model and/or the 4T1 mouse breast cancer model." (PMID 31578439, 2019). "Our results showed that both SMC1A and pSMC1A were expressed on the surface of breast cancer cells (MCF7, MDA-MB-231) but not on the normal cells (MCF10A, HPNE)." (PMID 39851557, 2025).
glioma (6 papers, 2015 to 2025). A benign or malignant brain and spinal cord tumor that arises from glial cells (astrocytes, oligodendrocytes, ependymal cells). "Our results are concordant with the outcome of SMC1A knocking down in both glioma and lung adenocarcinoma cells, in which cell proliferation was suppressed through G1/S or G2/M phase cell cycle arrest." (PMID 38365745, 2024). "Upregulation of SMC1A is involved in the pathogenesis of various tumors, such as gliomas, and colon, triple-negative breast, and liver cancers." (PMID 35372377, 2022). "In glioma, suppression of the SMC1A gene resulted in inhibition of tumor cell growth." (PMID 39851557, 2025). "Also, knocking down SMC1A inhibited growth and led to G2/M arrest in glioma cells." (PMID 25884313, 2015).
melanoma (6 papers, 2019 to 2025). A malignant, usually aggressive tumor composed of atypical, neoplastic melanocytes. "Another study demonstrated that LOXL3 interacted with proteins involved in DNA stability (e.g., BRCA2 and SMC1A) and mitosis completion to accelerate the proliferation of melanoma cells." (PMID 34307505, 2021). "To characterize the role of STAG2 in 3D genome organization in melanoma cells, we carried out ChIP-seq against STAG2, STAG1, SMC1A, and CTCF as well as Hi-C analyses in M14 melanoma cells stably expressing inducible shRNA of STAG26." (PMID 35388001, 2022).
leukemia (5 papers, 2013 to 2022). A malignant (clonal) hematologic disorder, involving hematopoietic stem cells and characterized by the presence of primitive or atypical myeloid or lymphoid cells in the bone marrow and the blood. "Mutations in DHX15 and SMC1A correlated with shorter OS in RUNX1/RUNX1T1 leukemia (DHX15: HR = 3.57, p = 0.02; SMC1A: HR = 6.47, p < 0.001), while point mutations in KIT at position D816 correlated with reduced RFS in RUNX1/RUNX1T1 leukemia (HR = 2.27, p = 0.046)." (PMID 31896782, 2020). "Given the results of other study, SMC1A mutations are neither significantly associated with X loss nor with gender in CBF leukemia patients, which indicated that homologous protein of SMC1A might exists in leukemia patients." (PMID 33928020, 2021).
liver cancer (5 papers, 2021 to 2023). An epithelial or non-epithelial malignant neoplasm that arises from the liver. "Moreover, SMC1A upregulation may be associated with the decreased OS of patients with colon and liver cancers." (PMID 35372377, 2022). "For example, SMC1A was first confirmed to be expressed at an abnormally high level in human liver cancer cell lines." (PMID 34527684, 2021). "In addition, the SMC1A phosphorylation is negatively correlated with the prognosis of patients with Tumor Node Metastasis (TNM) liver cancer stages III and IV." (PMID 34527684, 2021). "Phosphorylation of SMC1A promotes the invasion and metastasis of liver cancer cells." (PMID 34527684, 2021). "Recently, PIK3R3 was found to be upregulated in liver cancer; it activates Akt signaling to control cancer growth by regulating CDKN1C and SMC1A." (PMID 37644421, 2023). "SMC1A was partially responsible for PIK3R3 regulated function, and SMC1A overexpression rescued the impaired tumor cell growth in liver cancer cells." (PMID 37212524, 2023). "PIK3R3 is upregulated in liver cancer and activates Akt signaling to control cancer growth by regulation of CDNK1C and SMC1A." (PMID 37212524, 2023). "PIK3R3 is upregulated in liver cancer and activates Akt signaling to control cancer growth by regulation of CDNK1C and SMC1A.Targeting PIK3R3 could be a promising treatment strategy for liver cancer that deserves further investigation." (PMID 37212524, 2023). "Importantly, we verified that PIK3R3‐activated Akt signaling determined the expression of CDKN1C and SMC1A, two downstream of PIK3R3 in liver cancer cells." (PMID 37212524, 2023).
lung adenocarcinoma (5 papers, 2013 to 2024). A carcinoma that arises from the lung and is characterized by the presence of malignant glandular epithelial cells. "Shortened 3′UTR of SMC1A was seen in lung adenocarcinoma and had a significant association with clinical prognosis." (PMID 35487956, 2022). "Recently, SMC1A was found to be associated with cell growth and survival in lung adenocarcinoma and glioblastoma." (PMID 25884313, 2015). "Our results were coincident with the outcome of SMC1A silencing in lung adenocarcinoma cells, in which cell growth was suppressed through G0/G1 phase cell cycle arrest and apoptosis." (PMID 25884313, 2015). "In the present study, we determined the expression levels of SMC1A expression in lung adenocarcinoma A549 and H1299 cell lines using quantitative real-time PCR assay and western blot analysis, and observed clear expression of SMC1A in lung cancer cells." (PMID 23426528, 2013).
prostate carcinoma (5 papers, 2017 to 2025). A carcinoma that arises from epithelial cells of the prostate gland. "In a prior work, it was shown that SMC1A controlled EMT to mediate prostate cancer radioresistance." (PMID 37537540, 2023). "SMC1A is abundantly expressed in prostatic carcinoma, and knockdown of SMC1A might inhibit cell proliferation, growth, migration, and cancer stem-like cell features, while also improving the effectiveness of radiation treatment." (PMID 37537540, 2023). "In addition, in vivo experiment indicated that block of SMC1A impaired tumorgenesis of prostate cancer cells." (PMID 28868238, 2017). "We have shown for the first time the role of SMC1A in radio-resistance and regulating epithelial–mesenchymal transition (EMT) and cancer stem-like properties in prostate cancer cells." (PMID 39851557, 2025). "There is increasing evidence that SMC1A is closely associated with various cancer types, and our previous work has shown the role of SMC1A in the progression and metastasis of TNBC and metastatic castration-resistant prostate cancer cells." (PMID 39851557, 2025). "Next, SNVs in DNA repair genes (RAD51-associated protein 1 [RAD51 AP1], structural maintenance of chromosomes 1A [SMC1A], and activating signal cointegrator 1 complex subunit 3 [ASCC3]) were observed only in the RR prostate cancer cells." (PMID 39719436, 2024). "In prostate cancer, lncRNA TUG1 enhanced radioresistance through miR-139-5p/SMC1A axis." (PMID 35600868, 2022).
developmental and epileptic encephalopathy (4 papers, 2023 to 2026). An epilepsy associated with developmental impairment that may be due to either the underlying etiology or the superimposed epileptic activity, or both. "Germline mutations in the X-linked cohesin subunit gene SMC1A have been increasingly recognized as a cause of developmental and epileptic encephalopathy (DEE); however, the underlying basis of its marked phenotypic heterogeneity remains elusive." (PMID 41153413, 2025).
lung carcinoma (4 papers, 2013 to 2024). "To determine the role of SMC1A in lung cancer invasion, we tested the invasive ability of parent and Lv-shCon- or Lv-shSMC1A-infected A549 and H1299 cells using the Transwell chamber assay 96 h after infection." (PMID 23426528, 2013). "Collectively, these findings are the first report that SMC1A is a novel regulator of proliferation in lung cancer." (PMID 23426528, 2013). "Using a constructed lentivirus expressing SMC1A-specific shRNA, we infected A549 and H1299 cells to silence endogenous SMC1A and investigated the impact of SMC1A knockdown on the lung cancer development in vitro." (PMID 23426528, 2013). "Our observation found that SMC1A facilitates important regulatory roles in lung cancer cell proliferation and invasiveness." (PMID 23426528, 2013). "As result, we found that SMC1A is a novel oncogeme, which modulates the proliferation and migration capabilities of lung cancer cells via G1/S phase cell cycle arrest and apoptosis." (PMID 23426528, 2013). "In order to further investigate the role of SMC1A in the oncogenesis of lung cancer, SMC1A-specific short hairpin RNA (shRNA)-expressing lentivirus (Lv-shSMC1A) was constructed and used to infect A549 and H1299 cells." (PMID 23426528, 2013). "We adopted a lentiviral vector-mediated RNAi system to further determine the roles of SMC1A in the growth and invasive ability of lung cancer cells." (PMID 23426528, 2013). "Therefore, this indicates that the downregulation of SMC1A expression mitigates the invasion of lung cancer cells in vitro." (PMID 23426528, 2013). "This suggest that the downregulation of SMC1A expression may trigger apoptosis in lung cancer cells, contributing to the suppression of SMC1A cell growth." (PMID 23426528, 2013). "Therefore, this indicates the high efficacy of lentivirus-mediated SMC1A shRNA on SMC1A expression in lung cancer cells." (PMID 23426528, 2013). "Therefore, the low viability and colony-forming efficiency of Lv-shSMC1A-infected A549 and H1299 cells demonstrated that downregulation of SMC1A expression inhibits the growth of lung cancer cells in vitro." (PMID 23426528, 2013). "Consequently, this led to a hypothesis that, as an indispensible subunit of the cohesin complex, SMC1A may play a functional role in the biological behavior of lung cancer." (PMID 23426528, 2013). "Hence, this study extends our knowledge of the oncogenesis of lung cancer, and indicates that SMC1A may serve as a new molecular target." (PMID 23426528, 2013). "Furthermore, our study also showed that SMC1A knockdown may greatly reduce the migration capacity of the lung cancer cecolls, as evidenced by the Transwell chamber invasion assay." (PMID 23426528, 2013). "Therefore, SMC1A may serve as a new molecular target for lung cancer therapy." (PMID 23426528, 2013). "Downregulated expression of SMC1A, SMC3, and SMC4 could induce growth suppression in lung cancer cells via G1/S cell cycle phase arrest and the apoptosis pathway." (PMID 34336829, 2021).
myeloid neoplasm (4 papers, 2015 to 2025). Proliferation of myeloid cells originating from a primitive stem cell. "Recurrent mutations and deletions involving multiple components of the mitotic cohesion complex, including STAG2, RAD21, SMC1A and SMC3, were reported in different myeloid neoplasms." (PMID 26317787, 2015).
adenoma (3 papers, 2015 to 2025). A neoplasm arising from the epithelium. "Interestingly, in addition to SMC1A overexpression, carcinoma samples display more SMC1A mutations than adenomas and about 40% of carcinomas are characterized by carrying several SMC1A mutations in the same sample, suggesting that different clonal populations arise during cancer development." (PMID 30823889, 2019). "According to the Wilcoxon signed-rank test, the increase in SMC1A expression from normal mucosa to adenoma (p = 1.44 e-12) and from adenoma to carcinoma (p = 3.82 e-07) was highly significant." (PMID 30823889, 2019). "The expression of SMC1A was much stronger in CRC tumor tissues than in adenomas and normal colorectal tissues." (PMID 25884313, 2015). "Strong SMC1A expression in CRC tissues was significantly higher than that in matched adenoma and normal mucosa." (PMID 25884313, 2015). "Furthermore, the analysis of SMC1A expression in a larger cohort of patients (n = 66) showed that it is significantly more overexpressed in carcinomas than in both early adenomas and normal mucosa." (PMID 30823889, 2019). "In addition, SMC1A expression is significantly more robust in carcinomas than in normal mucosa and early adenomas." (PMID 30823889, 2019). "To investigate the levels of SMC1A expression during CRC development, we measured its expression in 66 subjects (including those analyzed by OncoScan assay) by immunochemistry, and again for each patient we analyzed normal mucosa, early adenoma and carcinoma." (PMID 30823889, 2019). "In addition, SMC1A expression is significantly higher in carcinomas than in normal mucosa and early adenomas." (PMID 39851557, 2025).